BIK (BCL2 interacting killer)
Diseases named in the same sentence as BIK in open-access papers (continued):
Sharing a sentence is not in itself a finding about the gene and the disease.
tumor (continued). "Research has shown that tumor cells can adapt to hypoxic conditions and resist hypoxia-induced cell death by altering their metabolism and physiological characteristics through the regulation of BIK expression, highlighting the intricate relationship between hypoxia and apoptosis." (PMID 38148838, 2023). "It was found that ATF3, and BIK were significantly overexpressed in tumor tissues, suggesting that these proteins may be involved in tumorigenesis and progression, particularly related to tumor cell proliferation, apoptosis inhibition, or microenvironment regulation." (PMID 40115255, 2025). "BCL-2 interacting killer (BIK) is a proapoptotic BH3-only member of the BCL-2 family and is prognostic for relapse and decreased overall survival of breast cancer." (PMID 32528057, 2020). "Though often overlooked, PD-L1 has several tumor intrinsic functions that have recently been identified to regulate mTOR/AKT, MAPK, STAT3/Caspase 7, integrin β4, MerTK, and BIM/BIK signaling, among others." (PMID 39663510, 2025). "At higher concentrations, autophagy and lysosome biogenesis genes, such as SQSTM1/p62, LAMP2, and PINK1, were robustly upregulated along with tumor suppressors, such as PTEN, and pro-apoptotic factors, including BAD and BIK, which reinforce autophagic flux and promote cellular homeostasis." (PMID 40671124, 2025). "The effect of PD-L1 on chemosensitivity was confirmed in BRAFV600E mutant MC38 murine tumor xenografts, where PD-L1 knockout cells were less sensitive to chemotherapy due to the suppression of pro-apoptotic molecules, BIM and BIK, compared to parental cells expressing PD-L1." (PMID 33193345, 2020). "Conversely, human colorectal cancer cells harboring a BRAFV600E mutation showed that the depletion of PD-L1 suppresses chemotherapy-induced apoptosis through the down regulation of BIM and BIK BH3-only proteins, even though depletion alone reduced tumor growth." (PMID 33193345, 2020). "This indicates a distinct pathway for metastasis, independent of the reported BIK-mediated apoptotic or tumor-suppressive function." (PMID 29203642, 2018). "BIK is a founding member of the BH3 family of pro-apoptotic proteins, and its high expression is usually studied to promote apoptosis, but it has been suggested that uncontrolled BIK-mediated chronic low-level cell death may lead to tumor cell adaptation and the evolution of aggressive tumor cells." (PMID 40438322, 2025). "However, active effectors (BAX and BAK) or initiator (PMAIP1, BIK and BID) cannot lead to apoptosis in tumours, and these pro‐apoptotic proteins may be sequestered by guardians (BCL2 and BCL2L1) that have more potent enhancer activity to propel the anti‐apoptotic mechanisms." (PMID 32419250, 2020).
cancer (29 papers, 2011 to 2025). A tumor composed of atypical neoplastic, often pleomorphic cells that invade other tissues. "Nevertheless, as seen with our study, ectopic BIK expression in the TNBC cell-line MDA-MB-231 can cause sublethal apoptosis-driven cancer aggression." (PMID 32528057, 2020). "We selected five genes (P57, CDK1, CDH2, E2F1 and BIK) that are quite relevant to cancer cell proliferation and apoptosis 24-28." (PMID 35371316, 2022). "CtBP proteins had been identified as anti-apoptotic proteins and negatively regulator through several program cell death genes, such as caspase-3, BIK and D3R, in human cancer cells." (PMID 34253710, 2021). "Combined with our previous results, these observations demonstrated that the BH3 domain of BIK and caspase activation are required for BIK-initiated sublethal apoptosis, increased DNA damage and subsequent cancer aggression." (PMID 32528057, 2020). "Studies have proven that activation of BIK can result in cancer cell death." (PMID 35371316, 2022). "In addition, we found that EXOSC4 knockdown caused the upregulation in mRNAs’ levels of BIK and SESN2, both of which induce apoptosis in cancer cells." (PMID 35008922, 2022). "Moreover, Maxfield and coworkers showed that FATE1 inhibits proapoptotic signaling in different cancer cell lines, by destabilizing the pro-apoptotic BCL2 interacting killer (BIK) protein." (PMID 33233365, 2020). "BIK-LTC-250 cell lines derived from both MCF-7 and MDA-MB-231 cells had ~1.7 times increased numbers of mammosphere colonies than their control EV-LTC-250 or BIK-LTC-0 cell lines, indicating that BIK-treatment increased the proportion of cancer stem-like cells." (PMID 32528057, 2020). "Taken together, these data are consistent with the proposition that BIK can facilitate heritable changes to pathways that increase the proportion of cancer stem-like cells, anchorage-independent growth, cell migration as well as colony-formation ability in the surviving cell population." (PMID 32528057, 2020). "Notably, BIK mRNA levels are significantly higher in hormonally-driven cancers compared to TNBCs, suggesting a minimum threshold of BIK is required to affect clinical outcomes." (PMID 32528057, 2020). "In addition, it has recently been observed that BIK is involved in autophagy in cancer cells." (PMID 27902785, 2016). "The mRNA stability of a proapoptotic gene BCL-2 interacting killer (BIK) is suppressed by La-related protein 1 (LARP1), a protein highly expressed in cancer cells." (PMID 41280104, 2025). "Consistent with this, we assessed the mRNA expression levels of SIRT1, EFNB3, and several apoptosis-regulating genes (BIK, CASP3, CASP4, and CASP9) in MCF-7 and MDA-MB-231 cancer cells." (PMID 24489730, 2014). "Our findings indicate that hESCs express elevated levels of the pro-apoptotic BH3-only BCL-2 family members NOXA, BIK, BIM, BMF and PUMA when compared with differentiated cells and cancer cells." (PMID 22174832, 2011). "Contrary to our expectations, we found that hESCs express the pro-apoptotic BH3-only BCL-2 family members NOXA, BIK, BIM, BMF, and PUMA at levels far greater than that seen in the seven human primary cells, hESC-derived neural stem cells, or cancer lines." (PMID 22174832, 2011).
infection (6 papers, 2016 to 2025). The state of being infected such as from the introduction of a foreign agent such as serum, vaccine, antigenic substance or organism. "Notably, all shCtr-treated mice succumbed to infection by 5 dpi, whereas 80% of the shBIK-treated mice survived, suggesting that reducing BIK levels in the airways significantly decreases susceptibility to IAV-induced morbidity and mortality." (PMID 40627391, 2025). "In human precision-cut lung slices (hPCLS), Cal/09 infection suppressed β5 and increased BIK protein levels at 24 and 48 hpi." (PMID 40627391, 2025). "Analysis of lung tissues 1 d post-infection (dpi) confirmed effective BIK silencing in the airways of shBIK-treated mice." (PMID 40627391, 2025). "Our data demonstrates that IAV actively induces BIK for productive infection." (PMID 40627391, 2025). "We found that, compared to vehicle-treated cells, both infection with IAV and treatment with MG132 inhibited the degradation of ubiquitin-conjugated BIK at 24 and 48 hpi." (PMID 40627391, 2025). "To assess the therapeutic potential of BIK silencing in the airways, we instilled WT C57BL/6 mice with retroviral vectors expressing either control shRNA (shCtr) or shRNA targeting BIK (shBIK) intranasally 2 d prior to infection with a lethal dose of PR/8." (PMID 40627391, 2025). "At 3 dpi, HIV-1-Luc/VSV-G infection in THP-1 cells was not significantly affected when BIK was depleted." (PMID 40434097, 2025). "Then, we further investigated whether HIV-1NL4-3 infection affected the interaction between SAMHD1 and BIK in THP-1 Ctrl cells using Co-IP." (PMID 40434097, 2025). "Overall, the BIK mRNA levels were higher in THP-1 Ctrl cells compared to SAMHD1 KO cells, regardless of HIV-1NL4-3 infection or NVP treatment, suggesting that SAMHD1 increases BIK expression at the mRNA level." (PMID 40434097, 2025). "At 4 and 6 dpi, we observed that the levels of BIK protein and mRNA in THP-1 Ctrl and SAMHD1 KI cells were higher than those in SAMHD1 KO and Lvx cells, regardless of HIV-1NL4-3 infection, suggesting that SAMHD1 increases BIK expression at both the protein and mRNA levels." (PMID 40434097, 2025).
BIK also shares sentences with these, for which no sentence is quoted: gastric cancer (3 papers); Multiple Myeloma (3); breast (2); adenovirus infection (1); esophageal cancer (1); fibrosarcoma (1); head and neck cancer (1); leukaemia (1); Oral Cancer (1); prostate tumors (1); rectal cancer (1); Splenomegaly (1); synovial sarcoma (1); triple-negative breast carcinoma (1); type 1 diabetes mellitus (1).